FGFR4 (fibroblast growth factor receptor 4)
Diseases named in the same sentence as FGFR4 in open-access papers (continued):
Sharing a sentence is not in itself a finding about the gene and the disease.
glioma (8 papers, 2016 to 2025). A benign or malignant brain and spinal cord tumor that arises from glial cells (astrocytes, oligodendrocytes, ependymal cells). "Nevertheless, a recent evaluation of transcriptomic glioma datasets from The Cancer Genome Atlas (TCGA) revealed a direct association of high FGFR4 expression and dismal prognosis, progressively upregulated in recurrent tumors." (PMID 36839989, 2023). "Overexpression of the receptor, FGFR4, has been observed in human glioma tissue compared to normal brain tissue, and overexpression is associated with poor prognosis and faster tumor recurrence." (PMID 42135822, 2025). "Regarding FGFR4, little information about its prognostic value has been published in the pediatric setting, with a few reports on glioma, MB, RMS and NB." (PMID 36839989, 2023). "It was reported that mutations of the FGFR1 kinase domain were found in human GBM tissue and the expression of FGFR1, FGFR3 and FGFR4 was increased in glioma." (PMID 37790751, 2023). "Pharmacological FGFR inhibition by either the multi-TKI ponatinib or the FGFR4-specific drug BLU554 sensitized FGFR4high glioma cells towards integrin-targeting." (PMID 35484633, 2022). "Consistently, in vitro and in vivo (zebrafish larvae) data demonstrated a supportive role for FGFR4 in GBM cell migration, invasion, and adhesion, which was corroborated by gene expression analyses of our FGFR4-engineered glioma cell models and the TCGA-GBM data cohort." (PMID 35484633, 2022). "FGF signaling pathway including FGFR1, FGFR4 and FGFR23 was shown to be involved in recruiting immunosuppressive cells, regulating M2 polarization of GAMs and T cell exhaustion in gliomas." (PMID 37790751, 2023). "Accordingly, introduction of FGFR4-KD(K504M) impaired GBM clonogenicity and cell proliferation, especially in the endogenously FGFR4high glioma models (respectively)." (PMID 35484633, 2022). "The majority of these patients were FGFR3-TACC3 positive, but we also observed 1 case of a FGFR2-INA fusion that was originally described in gliomas, and 2 novel FGFR fusions, including SLC20A2-FGFR1 and FGFR4-GAPGEFL1." (PMID 33710807, 2021). "In the context of gliomas, the literature suggests that the GDNF–RET pathway and FGFR4 signaling may contribute to progression and treatment resistance in subsets of brain tumors." (PMID 41517303, 2025).
Insulin resistance (8 papers, 2011 to 2023). Increased resistance towards insulin, that is, diminished effectiveness of insulin in reducing blood glucose levels. "This is associated with improved NAFLD activity score and insulin resistance, implicating hepatic FGFR4 as an interesting target for the management of NAFLD." (PMID 36586437, 2023). "Fgfr4−/− knockout mice exhibited glucose intolerance and insulin resistance, while FGFR4 polymorphisms can increase insulin secretion in mice pancreatic islets." (PMID 34035238, 2021). "A study in FGFR4-deficient mice on a normal diet exhibited features of the metabolic syndrome, including increased mass of white adipose tissue, hyperlipidemia, hypercholesterolemia and insulin resistance." (PMID 24260100, 2013). "Briefly, Fgfr4-/- mice fed a normal chow diet exhibit insulin resistance and impaired glucose tolerance compared to wild-type controls, however, this difference is not observed in high-fat diet fed mice where both groups showed signs of insulin resistance." (PMID 36823471, 2023). "A whole-body knockout of FGFR4 in mice on chow diet induced features of metabolic syndrome including increased adiposity, hyperlipidemia, and insulin resistance." (PMID 36586437, 2023). "Insulin resistance, assessed by Homeostatic Model Assessment of Insulin Resistance (HOMA-IR), was significantly increased in HFD-fed mice and restored by KD of FGFR4 to the level observed in chow-fed mice." (PMID 36586437, 2023). "Surprisingly, while restoration of FGFR4 selectively in hepatocytes in the FGFR4-KO mice normalizes plasma lipid levels, it fails to restore the glucose intolerance and insulin resistance." (PMID 32372975, 2020). "In addition to the effects in insulin resistance and glucose metabolism, FGF19 increases serum BHB levels even in Fgfr4 KO mice, like FGF21." (PMID 21437243, 2011). "However, a whole-body KO of FGFR4 in mice on HFD improved hepatic lipid accumulation, but not dyslipidemia or insulin resistance." (PMID 36586437, 2023).
non-small cell lung carcinoma (8 papers, 2016 to 2025). A group of at least three distinct histological types of lung cancer, including non-small cell squamous cell carcinoma, adenocarcinoma, and large cell carcinoma. "According to these results, we established a novel nomogram based on the mutation of FGFR4, TMB level, PD-L1 expression, and other clinicopathological parameters for advanced non-small cell lung cancer patients with immune checkpoint inhibitors." (PMID 33407583, 2021). "FGFR4 fusions are rare, and only some cases were reported in non-small cell lung cancer (NSCLC)." (PMID 34732230, 2021).
Cirrhosis (7 papers, 2015 to 2022). A chronic disorder of the liver in which liver tissue becomes scarred and is partially replaced by regenerative nodules and fibrotic tissue resulting in loss of liver function. "Moreover, the expression of both FGFR3 and FGFR4 was significantly associated with cirrhosis (p < 0.05) while FGFR4 was also upregulated in HCV-positive HCC patients (p < 0.002)." (PMID 35683481, 2022). "Previously, FGFR4 dysregulation was reported in patients with nonalcoholic steatohepatitis or cirrhosis." (PMID 35683481, 2022). "On the contrary, FGFR4 was markedly reduced in severe fibrosis or cirrhosis samples compared to mild fibrosis." (PMID 32587612, 2020). "On the contrary, FGFR4 expression was significantly downregulated in severe fibrosis or cirrhosis samples compared to mild fibrosis samples, and it was much lower in cirrhosis samples compared with severe fibrosis samples." (PMID 32587612, 2020). "FGF19, FGFR4 and EpCAM expressions between the different histologic stages of fatty liver steatohepatitis-cirrhosis-HCC carcinogenesis sequence were compared to healthy hepatic tissue." (PMID 27447573, 2016). "Compared with severe fibrosis samples, FGFR4 expression was significantly dropped in cirrhosis." (PMID 32587612, 2020). "FGFR4, ubiquitous protein that has a key role in extracellular matrix (ECM) turnover during fibrogenesis, may be associated with the risk of HCC coupled with liver cirrhosis and cirrhosis." (PMID 27099671, 2016). "The clinicopathological analyses were performed for FGFR1, FGFR2, FGFR3 and FGFR4 against age, sex, grade stages, tumor stages, HCV, AFP, cirrhosis, vascular invasion, and cell type (atypical, dysplastic/polygonal, neoplastic) using different statistical approaches." (PMID 35683481, 2022). "Moreover, FGFR3 and FGFR4 showed a significant upregulation in advanced stages of HCC patients.The results from three independent cohorts suggested a strong positive correlation between FGFR2 expression and HCV-positive cirrhosis patients as well as HCV-positive HCC patients." (PMID 35683481, 2022). "Interestingly, FGFR4 overexpression was more common in HCC patients with no cirrhosis." (PMID 35683481, 2022).
diabetes (7 papers, 2012 to 2025). "Expression of FGFR4 in liver was found to be decreased by fasting, increased by insulin, and reduced by streptozotocin-induced diabetes, implicating FGFR4 as a primary target of insulin regulation." (PMID 23922646, 2013). "Hepatic FGFR4 expression is decreased by fasting, increased by insulin, and reduced by streptozotocin-induced diabetes." (PMID 23922646, 2013). "No therapies specifically target FGF23 to lower diabetes risk, but fibroblast growth factor receptor 4 (FGFR4) inhibitors show promise." (PMID 40237064, 2025). "Moreover, hepatic expression levels of FGF21, CYP7A1, HNF4α, β-Klotho, FGFR4, and GS were higher in T2D patients that do not remit diabetes after RYGB surgery." (PMID 25664662, 2015). "A common pattern emerged whereby patients that do not remit diabetes (T2D-NoR) displayed signifciantly higher expression levels for FGF21, HNF4α, CYP7A1, β-Klotho, GS, and FGFR4, compared to the No-T2D and T2D-R groups." (PMID 25664662, 2015).
glioblastoma (7 papers, 2022 to 2025). The most malignant astrocytic tumor (WHO grade IV). "Recent literature has shown that FGFR4 can promote glioblastoma and that the Arg388 allele increases STAT3/EMT signaling in other tumors." (PMID 41517303, 2025). "FGFR4 expression is physiologically low in the brain but is increased in tumors such as glioblastoma, where it enhances integrin-mediated cell adhesion and invasion." (PMID 40393028, 2025). "While little is known about the role of FGFR2 and FGFR4 in glioblastoma, FGFR1 is expressed in human glioma, and its expression level increases with the grade of malignancy." (PMID 35955806, 2022). "Glioblastoma stem cell (GSC) models exhibited comparably high FGFR4 mRNA levels." (PMID 35484633, 2022). "Despite widely absent in adult brain, FGFR4 mRNA was distinctly expressed in embryonic neural stem cells and significantly upregulated in glioblastoma." (PMID 35484633, 2022). "The alterations in FGFR4, KIT, and PEG3 were correlated with a short OS in astrocytoma, alterations in CDK4, FUBP1, and NTRK2 were correlated with a short OS in oligodendroglioma, and alterations in CDK4, CIC, FGFR3, and KMT5B were correlated with a short OS in glioblastoma." (PMID 36998447, 2023). "A whole genome analysis of more than 2662 adult human glioblastoma samples revealed the number of FGFR-aberrations and amplifications as generally sparse, with prevalence of FGFR1 aberrations of 51 in 3068, FGFR2 in 12 of 2662, FGFR3 in 13 of 2887, and FGFR4 in 9 out of 2456 investigated samples." (PMID 35955806, 2022).
metastatic disease (7 papers, 2006 to 2025). "Based on the strong correlation between HNF1A and FGFR4 expression in metastatic disease, we next sought to validate FGFR4 as a direct target gene of HNF1A." (PMID 40731412, 2025). "Because the large majority of patients that undergo surgery will succumb to metastatic relapse, FGFR4 inhibition before surgery could improve the potential for cure with resection by preventing recurrent metastatic tumors." (PMID 40731412, 2025). "Using RNA-sequencing datasets from the European Genome Phenome Archive EGAD00001003584 and EGAD00001004548) and CPTAC, we additionally found a positive and significant correlation in HNF1A and FGFR4 RNA levels in patient samples from both primary and metastatic tumors." (PMID 40731412, 2025). "Considering that the clinical behavior of tumors harboring specific genetic aberrations may be different between localized resectable and metastatic disease, our data on prognosis may have some limitations for indicating the impact of high FGFR4 expression in patients with metastatic iCCA." (PMID 28445152, 2017). "Knockdown of HNF1A significantly depleted metastatic tumors, and HNF1A overexpression significantly increased cell migration and invasion in several PDAC cell lines, which was abrogated by FGFR4 genetic knockdown and pharmacological inhibition." (PMID 40731412, 2025). "Though FGFR4 inhibitors are unlikely to deplete existing metastatic tumors as they are not cytotoxic, preventing or delaying further lesions could allow standard of care chemotherapies to prove more efficacious and extend survival." (PMID 40731412, 2025).
bladder cancer (6 papers, 2006 to 2026). "Accordingly, FGFR4, a risk factor for various cancers including urinary bladder carcinoma, may deteriorate over the course of UCC with different SNPs, which was supported by the results of the current study." (PMID 31878098, 2019). "The impact of the fibroblast growth factor receptor 4 (FGFR4) Gly388Arg polymorphism on bladder cancer is unknown." (PMID 17088904, 2006). "The receptor tyrosine kinase ERBB2 was primarily amplified in bladder cancer, while FGFR4 and EGFL7 alterations were mainly seen among RCC cases." (PMID 38398121, 2024). "We found no clear correlations between the FGFR4 genotype and risk of bladder cancer or pathological parameters." (PMID 17088904, 2006). "However, the molecular mechanisms of the FGFR4 Gly388Arg polymorphism has not been examined in human bladder cancer." (PMID 17088904, 2006). "For example, the database BoostDM only covers FGFR3 based on mutational data from bladder cancer and provides no information at all for FGFR1, FGFR2 or FGFR4." (PMID 41361008, 2026).
breast tumors (6 papers, 2013 to 2026). "Consistently, FGFR4/FGF19 co-expression was also observed in 82 out of 287 (28.6%) primary breast tumors, and their expression is strongly associated with AKT phosphorylation, Ki-67 staining, higher tumor stage and basal-like phenotype." (PMID 27192118, 2016). "We observed in metabolic pathways by quantitative PCR analyses that NAMPT is overexpressed in breast tumor tissue and FGFR4 deficiency downregulates the expression." (PMID 24279986, 2013). "The overall survival and breast tumor-specific survival rates were both higher in the FGFR4-deficient TGFα transgenic mice than the FGFR4-WT TGFα transgenic mice." (PMID 24279986, 2013). "NAMPT as a downstream target of FGFR4 deficiency and FGF21 elevation is highly expressed in breast tumor foci but attenuated by the FGFR4 deficiency." (PMID 24279986, 2013). "The effects of the FGFR4 deficiency on breast tumors are most likely through these systemic indirect metabolic effects that modify the local adipose tissue microenvironment and epithelial compartment in breast duct and lobular structures and the developing malignant cells." (PMID 24279986, 2013). "We thus proceeded to perform analyses of the effect of the FGFR4 deficiency on expression of major regulatory and enzyme genes involved in the pathways of adipogenesis, fatty acid metabolism, glucose metabolism and mitochondrial function in normal breast and breast tumor." (PMID 24279986, 2013). "Recently, two studies reported that FGFR4 acts as an important mediator of endocrine resistance and metastasis in invasive lobular carcinoma and luminal A primary breast tumours (HER2-negative) that gives rise to HER2-enriched metastases." (PMID 35193394, 2022). "Breast tumors were induced in the bigenic mice with ablation of FGFR4 and overexpression of TGFα that activates Her2 in the ductal and lobular epithelium surrounded by adipocytes." (PMID 24279986, 2013). "Genetic knockout of FGF19 or inhibition of FGFR4 has been demonstrated to inhibit breast tumor progression and metastasis in mouse models, suggesting that targeting FGFR4 may be a viable therapeutic strategy for cancer suppression." (PMID 41328353, 2026). "Finally, the role of FGFR4 in resistance has been recently confirmed also in TNBCs, thus expanding the repertoire of breast tumours where FGFR4 signalling plays an important but still understudied role." (PMID 35193394, 2022). "Finally, using a panel of well-validated tissue microarray, we show that a subset of primary breast tumors co-expresses FGFR4 and FGF19." (PMID 27192118, 2016). "In tissue samples obtained from consecutive surgeries of primary human breast tumors, FGFR1 was most abundantly expressed at the mRNA level, followed by FGFR4 and FGFR2." (PMID 33119860, 2021). "We thus turned to the systemic metabolic activities of FGFR4 as a potential source of the negative impact on breast tumor progression." (PMID 24279986, 2013). "Importantly, FGFR4, FGF19 and phospho-AKT were found to be co-overexpressed in a subset of basal-like breast tumors, suggesting that the FGFR4/FGF19 autocrine loop might be of clinical importance." (PMID 27192118, 2016). "However, the absence of FGFR4 reduced TGFα–driven breast tumor incidence and progression and improved host survival." (PMID 24279986, 2013).
cervical cancer (6 papers, 2016 to 2024). A primary or metastatic malignant neoplasm involving the cervix. "Cox regression analysis confirmed that FGFR2, FGFR3, and FGFR4 expression was an important prognostic indicator in cervical cancer." (PMID 27154171, 2016). "In conclusion, the present study investigated the immunohistochemical expression of FGFR1, FGFR2, FGFR3, and FGFR4 in a large number of cervical cancer patients." (PMID 27154171, 2016). "In the present study, we investigated the prognostic significance of FGFR1, FGFR2, FGFR3, and FGFR4 expression in a large cohort of cervical cancer patients." (PMID 27154171, 2016). "Thus, the aim of this study is to investigate the clinical significance of FGFR1, FGFR2, FGFR3 and FGFR4 expression in a well-defined cohort of cervical cancers, using immunohistochemistry and quantitative digital image analysis." (PMID 27154171, 2016). "Furthermore, we demonstrate for the first time that elevated expression of FGFR2, FGFR3, or FGFR4 predict favorable survival in cervical cancer patients." (PMID 27154171, 2016). "FGFR1, FGFR2, FGFR3, and FGFR4 expression was determined by immunohistochemistry in conjunction with quantitative digital image analysis of 336 formalin-fixed, paraffin-embedded cervical cancer tissues and 61 normal cervical tissues, as well as NCI60 cell microarray." (PMID 27154171, 2016).
hyperphosphatemia (6 papers, 2016 to 2025). Abnormally high level of phosphate in the blood. "Mice expressing constitutively active FGFR4 developed cardiac remodeling despite normal serum phosphate levels, whereas global and cardiac-specific FGFR4 knockout mice were protected from cardiac remodeling despite CKD-associated hyperphosphatemia." (PMID 39923962, 2025). "The dose-limiting toxicities due to inhibition of FGFR1/FGFR3 and FGFR4 are hyperphosphatemia and the blockade of bile acid synthesis, respectively." (PMID 27029060, 2016). "Second, FGFR4 does not significantly modify calcification, renal dysfunction and mortality in kl/kl mice suggesting that hyperphosphatemia and α-klotho deficiency per se are the main drivers of senescence and renal injury." (PMID 31575945, 2019). "Multiple pan-FGFR inhibitors have shown weak efficacy against FGFR4 together with toxicity (hyperphosphatemia and soft tissue mineralization) due to activity against FGFR1 ∼ 3, which indicates a strong need for the discovery of FGFR4-selective inhibitors." (PMID 35296193, 2022). "We expose mice constitutively lacking FGFR4 to hyperphosphatemia in the absence and presence of CKD." (PMID 35302487, 2022). "Ablation of FGFR4 in mice did not improve skeletal muscle function following adenine or 3% Pi diets, suggesting hyperphosphatemia rather than pathologic FGF23-FGFR4 signaling might be the cause of skeletal muscle abnormalities." (PMID 35302487, 2022).